INS (insulin)
Diseases named in the same sentence as INS in open-access papers (continued):
Sharing a sentence is not in itself a finding about the gene and the disease.
diabetes (continued). "Compared with type 1 diabetes, DM in WS1 patients is characterized by a lower, daily insulin requirement and a milder clinical course than type 1 diabetes." (PMID 35010780, 2022). "Diabetes is a metabolic pathology with chronic high blood glucose levels that occurs when the pancreas does not produce enough insulin or the body does not properly use the insulin it produces." (PMID 36297570, 2022). "Exogenous insulin could keep hyperglycemia under control, but it is insufficient to reduce diabetes-related complications because it is not as effective and dynamic as endogenous insulin." (PMID 36451229, 2022). "Patients with diabetes have abnormal glucose metabolism due to an absolute or relative lack of insulin in the body, which is also accompanied by abnormalities in lipid and protein metabolism, which mainly manifest as alterations in the circulating levels of many metabolites." (PMID 35456051, 2022). "The remission of diabetes depends on multiple factors that are not assessed in this study, such as age, sex, duration of the disease, drug treatment with oral hypoglycemic agents or insulin, and pancreatic reserve." (PMID 35790676, 2022). "However, while physicians in this study think that most of their patients fear needle injections (80.5%), studies on diabetes patients reveled that fear of needle injections was not the most common reason for their refusal to initiate insulin." (PMID 36554673, 2022). "However, ten weeks of intensive atorvastatin (40 mg/d) treatment increased the emergence of insulin resistance and insulin secretion in participants without diabetes." (PMID 36589857, 2022). "Given, the hazardous consequences of non-adherence to insulin on diabetes outcomes, in addition to the availability of evidence which shows that psychosocial factors such as beliefs, attitudes, and motivation have a greater influence on adherence than personality, metabolic, and demographic factors." (PMID 35673417, 2022). "Furthermore, neither does he follow any dietary restriction for his diabetes or G6PD deficiency, nor does he correctly apply the insulin dose." (PMID 35444908, 2022). "Importantly, there is no data on medication regimen and adherence for both insulin and oral medication for diabetes." (PMID 36516178, 2022). "However, the Diabetes Control and Complication Trial (DCCT) reported that intensive insulin therapy in the form of continuous subcutaneous insulin infusion, or three or more injections per day, resulted in better glycemic control than conservative therapy in the form of two injections per day." (PMID 36141857, 2022). "However, the Stent Restenosis and Metabolism (STREAM) study showed that addition of a single bedtime dose of insulin in patients with diabetes does not influence ISR." (PMID 35669469, 2022). "Among the 634 patients with diabetes who did not use any antihyperglycemic drugs at randomization, the proportions of patients who initiated treatment with non-insulin antihyperglycemic medications were similar between treatment groups (13.7% vs. 15.7%; HR: 0.88, 95% CI 0.58–1.32, P = 0.53)." (PMID 35717169, 2022). "People with diabetes, their insulin would be damaged since there was no electricity." (PMID 36380330, 2022). "Therefore, whether the intervention of ATMs or ATMs-sEVs can reduce weight or treat diabetes warrants further research, and the study of the key miRNA/miRNAs within lean ATM-Exos (LATMs-sEVs) improving insulin sensitivity is worthy of future investigation." (PMID 35832790, 2022). "However, we demonstrated that diabetes control (measured by HbA1c) was not influenced by the methods of insulin administration (p = 0.549) and therefore do not believe that this should impact on the study findings." (PMID 36158626, 2022). "Importantly, insulin preparations used for diabetes treatment also form these two types of amyloids without TCEP11." (PMID 35595809, 2022).
diabetes (continued). "In addition, homozygous mutations in some MODY genes can cause other types of diabetes, such as permanent neonatal diabetes and antibody-negative type 1 diabetes mellitus (T1DM) caused by mutations in the insulin gene (INS; MODY10)." (PMID 36613572, 2022). "JAK2 has a negative impact on synapse formation and insulin sensitivity in diabetes." (PMID 35578689, 2022). "Furthermore, oral administration of PEC/alginate-coated insulin promoted upregulation of insulin in diabetic rats; therefore, PEC alginate combination could be used as a therapeutic option for the treatment of diabetes." (PMID 35155670, 2022). "This high proportion in our study site may be due to the underuse of standard diabetes treatment guidelines, initiation of insulin-based regimens without clear indications, and initiation of anti-diabetics when non-drug therapy is more appropriate." (PMID 35767589, 2022). "In a study of 16 dogs with canine AD, ciclosporin (5 mg/kg/day; six weeks) significantly increased glucose levels and decreased serum insulin concentrations, whereas fructosamine levels (statistically increased) remained within the normal range and no dog developed diabetes mellitus." (PMID 35448647, 2022). "Interestingly, it has been shown that visceral adiposity precedes the development of T2DM and exhibits an effect independent of fasting insulin, insulin secretion, glycemia, total and regional adiposities, and family history of diabetes." (PMID 36523689, 2022). "In diabetes mellitus, the pancreas prepares insulin but body cells do not recognize it." (PMID 36296403, 2022). "However, even if the diabetes duration is longer in patients treated with insulin, this does not fully explain the occurrence of DPN, which can be encountered in 11–25% as early as the pre-diabetes stage." (PMID 36611296, 2022). "This may identify ak as a candidate treatment target for diabetes, as it could be used to increase insulin secretion, without disrupting the homeostasis of the β-cell." (PMID 36251711, 2022). "In addition, insulin plays an important role in regulating SBP independently of diabetes, with evidence that insulin is correlated with SBP in non-diabetic individuals." (PMID 36589843, 2022). "Given the reduced emphasis of sex differences in diabetes research and the limited studies in T1D females, we designed a study to examine the impact of aerobic exercise training independent of insulin therapy on glucose homeostasis and skeletal muscle metabolism in T1D female mice." (PMID 36295850, 2022). "Diabetes is the most common disease of the endocrine system and is triggered when the amount of insulin secreted in the body is not optimal or when peripheral cells do not respond to its action (insulin is a hormone that lowers blood glucose)." (PMID 35198096, 2022). "Taking in account that oxygen reactive species (ROS) and oxidative stress have been reported as the main factors for impaired insulin secretion, glucose mobilization and consequently DM2, cinnamon could be used as a coadjutant for oxidative management preventing diabetes." (PMID 35458138, 2022). "A case report by Nadine E Palermo found a 53 years woman who presented to the emergency department in Boston with elevated biochemical cytokines, but she had no diabetes‐related complications before her admission and was started IV insulin with the supportive treatment of ketoacidosis." (PMID 35212184, 2022). "Similarly, three studies utilizing medication possession ratios observed that 31-46% of patients that were prescribed oral diabetes medications alone or in addition to insulin were non-adherent." (PMID 35619860, 2022). "PAK1 is involved in the second phase of glucose-stimulated insulin secretion and Islets from individuals with T2D have been found deficient in PAK1 protein expression when compared with islets of individuals without diabetes." (PMID 35227251, 2022).
diabetes (continued). "An in-depth understanding of how hyperglycemia levels and imbalances in insulin regulation mechanisms act on the rt-PA intravenous thrombolytic process and thus affect the benefits of postvenous thrombolytic nerve function in patients with AIS with diabetes mellitus is critical." (PMID 36324389, 2022). "In the present study, the duration of diabetes was 10.7 ± 8.3 years, and these results may have been influenced by long-term inappropriate insulin treatment that failed to adequately regulate blood glucose." (PMID 35268317, 2022). "In addition, it should be noted that the literature reviewed here includes studies focused on those with diabetes, not specifically those using insulin, due to the extremely limited evidence of dietary intake among those using insulin." (PMID 36014790, 2022). "First, we did not account for the effect of diabetes type and diabetes medications like insulin and metformin; thus, we were unable to assess whether medications and diabetes type have an effect on outcomes at this point." (PMID 36699043, 2022). "(2020) proposed insulin resistance and possibly insulin secretory abnormalities, which could precipitate hyperglycemia in patients with COVID-19, even in the absence of pre-existing diabetes." (PMID 36992767, 2022). "Many young and middle-aged women do not use insulin or anti-diabetes, or anti-cholesterol drugs." (PMID 36479374, 2022). "Based on previous studies, Jang suggests MODY genetic analysis in adult diabetic patients if they were diagnosed before the age of 30, if β-cell antibodies are negative, and if they have a family history of diabetes and BMI ≤ 30 kg/m2 without insulin resistance." (PMID 35029855, 2022). "However, in clinical practice, fasting insulin levels are not routinely measured even in diabetics, let alone in individuals without diabetes." (PMID 36452320, 2022). "In a subset of mice from the current study (WT and AD groups with the sham surgery), we previously reported that 3xTg-AD females did not display increased plasma levels of other diabetes markers (e.g., insulin, GIP, GLP-1, PAI-1, resistin) or peripheral inflammation." (PMID 35568928, 2022). "Studies focusing on participants with cardiovascular diseases rather than with increased cardiovascular risk are almost lacking, and the same goes for trials with persons with diabetes where no data are available on the effects of Aronia on insulin secretion and sensitivity." (PMID 35831939, 2022). "In contrast, insulin showed a strong colocalization with Rab11A (PCC 0.63 ± 0.09) or Rab11B (PCC 0.61 ± 0.06), which significantly decreased (p < .001) following induction of diabetes (colocalization of insulin with Rab11A, PCC 0.35 ± 0.5, or Rab11B, PCC 0.38 ± 0.07)." (PMID 34923907, 2022). "Fifth, information on glucose-lowering therapies in subjects with diabetes was limited; the specific types of antidiabetic drugs or insulin therapy were not obtained in this study, although our sensitivity and subgroup analyses indicate that this did not influence the conclusions of our study." (PMID 36079764, 2022). "The possible reason for this elevation may be the chronic inflammatory effect of diabetes, which develops due to the absence of insulin and is accompanied by low NK-cell activity." (PMID 34174798, 2022). "MODY is a type of monogenic diabetes characterized by early-onset (age of diagnosis is usually before 25), autosomal dominant inheritance, no autoimmune process or insulin resistance, retention of endogenous insulin secretion, and no dependence on insulin." (PMID 35299962, 2022). "At randomization, there were 1738 patients with diabetes who did not use insulin." (PMID 35717169, 2022). "It is rather concerning that nearly about three-fourths of participants were not aware that diabetes can be controlled through physical exercise, regulated diet intake and recommended medication including insulin when needed, which is very low in contrast with another study." (PMID 36466517, 2022).
diabetes (continued). "While it was clear some people with diabetes in this study knew they would not respond well to generic insulin, others may have been unaware of the generic insulin option." (PMID 35436214, 2022). "In MafA-/- mice, insulin 1, insulin 2, PDX-1, neurogenic differentiation (NeuroD) and glucose transporter 2 (GLUT2) amounts are reduced, and glucose, arginine and KCl-induced insulin secretion are remarkably altered Thus, PDX-1 and MafA may be important factors in diabetes therapy." (PMID 35656076, 2022). "Overall, the results revealed that TBF exerted antidiabetic effects in the two diabetes models, and these effects may be mediated not through changes in insulin signal-related pathways, but instead may be related to the regulation of gut microbiota dysbiosis." (PMID 36016679, 2022). "This severe metabolic complication is typically associated with Type 1 diabetes mellitus (T1DM), as a first presentation or as a consequence of non-optimal insulin therapy management; however, it can occasionally affect Type 2 diabetes mellitus (T2DM) patients." (PMID 35718795, 2022). "Furthermore, worse clinical outcomes found in HFpEF patients with insulin-treated diabetes versus diabetes not treated with insulin require further mechanistic investigation." (PMID 36575484, 2022). "The same PN admixtures may be used for patients with and without diabetes with additional insulin administration." (PMID 36992742, 2022). "Furthermore, sacubitril/valsartan has been shown to improve measures of insulin sensitivity in obese patients who did not have diabetes or heart failure." (PMID 35717169, 2022). "We found that this plant-derived silicon not only restored serum insulin concentrations and improved glucose tolerance, but also ameliorated liver tissue damage and reversed the expression of glucose-metabolism-related markers in a STZ-induced diabetic mouse model." (PMID 36295866, 2022). "However, none of the patients with hypothyroidism and diabetes had to adjust their doses of levothyroxine or insulin during DHEA exposure." (PMID 36142945, 2022). "Insulin is not used in sole PCOS without the complication of diabetes mellitus." (PMID 35564864, 2022). "However, other studies have reported a potential benefit of folic acid supplementation on insulin resistance and glycemic control, but no clear effect on the development of diabetes." (PMID 35951607, 2022). "In addition, we did not account for changes in diabetes medication during the study, including initiation of insulin treatment." (PMID 36062034, 2022). "Previous investigations described insulin resistance as an intrinsic defect of non-insulin-dependent diabetes, irrespective of obesity, being the deleterious effect of diabetes on in vivo insulin-stimulated glucose utilization much greater than that of obesity." (PMID 36614099, 2022). "The patients were T2DM, and about 2/3 received statins, and nearly 1/3 insulin; all had previously undergone coronary calcium score (CCS) screening using CT and NaF PET/CT as baseline assessments for a trial on the arterial effects of vitamin K1 and colchicine in subjects with diabetes." (PMID 36142181, 2022). "Healthy individuals are highly responsive to insulin in skeletal muscle, liver, and adipose tissue, whereas obese or type 2 diabetes mellitus (T2DM) individuals do not exert any reaction to the presence of insulin and, for this reason, are called insulin-resistant." (PMID 35741464, 2022). "Diabetes is due to either lack of insulin secretion from the β cells in the pancreas or insulin resistance, a condition in which cells of the body do not respond properly to insulin." (PMID 35741012, 2022). "Our results align with these mechanisms, indicating that the modulating effect of fasting insulin on SBP could be independent of (direct effects) or via (indirect effects) diabetes." (PMID 36589843, 2022).
diabetes (continued). "However, the examination of fasting insulin is not routinely performed in daily clinical processes, even for patients having experienced diabetes mellitus." (PMID 36312238, 2022). "Type 1 diabetes mellitus (T1DM) is identified as a chronic autoimmune disease marked by selective autoimmune-regulated damage of pancreatic islet beta-cells, which can cause an absolute lack of insulin." (PMID 36514009, 2022). "Notably however, despite the significant decrease in blood glucose levels over time and 10 days after treatment, total insulin content was not improved in islets from NDM mice when therapy was initiated at >42 days of diabetes." (PMID 35180212, 2022). "This might be explained by the lower insulin concentrations in the Diabetes-β-Cell-Failure group compared to the Diabetes-Absent group." (PMID 36211668, 2022). "Dysregulated insulin secretion in diabetic and non-diabetic older individuals may play an important role in age-related and diabetes-related sarcopenia." (PMID 36482911, 2022). "Nevertheless, patients with diabetes have impaired diastolic function both at rest and during exercise when compared to healthy controls, while the insulin-induced rise in LVEF is significantly lower in those patients when compared to healthy subjects due to insulin resistance." (PMID 36289641, 2022). "Cerebrovascular disease and vascular dementia are also strongly related to insulin resistance, even independent of frank diabetes, and the Insulin Resistance Intervention after Stroke (IRIS) trial established that improving insulin sensitivity can prevent cerebrovascular events." (PMID 33717095, 2021). "American Diabetes Association (ADA) and the American College of Obstetricians and Gynecologists (ACOG) preferably recommend initiation of pharmacotherapy with insulin, but there are conditions when implementation of insulin is impractical or not possible." (PMID 34440947, 2021). "Diabetes mellitus is a chronic non-infectious medical condition which is evident by raised levels of glucose in the blood, because the body cannot produce any or enough of the hormone insulin or use insulin effectively." (PMID 33541316, 2021). "According to the results of the current study, decreased bodyweight together with improved glucose and insulin tolerance in RAGE−/− mice, the absence of RAGE may conceivably reduce the risk of developing diabetes in mice." (PMID 34686659, 2021). "Some authors suggested that almost all T1DM (type 1 diabetes mellitus) patients would have some degree of retinopathy 20 years from T1DM diagnosis, as would more than 80% of insulin-treated T2DM (type 2 diabetes mellitus) patients and 50% of those not requiring insulin." (PMID 33728349, 2021). "Yet, in our data on islet transplantation, we demonstrated that DIU was associated with similar HbA1c values to donors not treated with insulin, thereby excluding the pre-existing diabetes hypothesis." (PMID 33665687, 2021). "Significantly higher proportions of RPC were found in patients with a family history of diabetes (χ2 test, p = 0.002), longer diabetes duration (p<0.001), insulin treatment (p<0.001), nondrinker (p = 0.009) and lower level of PA (p = 0.006), compared to otherwise." (PMID 33444338, 2021). "Diabetes is an endocrinological disorder that dysregulates several metabolic processes and so forth alters the levels of a multitude of metabolites and signaling molecules, either due to lack of insulin or insulin signaling." (PMID 33918273, 2021). "In patients with a family history of diabetes, the delightful change in 1 year was an improvement of ISIm, and this continued in the 2nd year with improved HOMA-IR; however, HOMA-B and Insulinogenic index, which represented insulin secretion, worsen in the 2nd year." (PMID 33490287, 2021).